EWSR1 (EWS RNA binding protein 1)
Diseases named in the same sentence as EWSR1 in open-access papers (continued):
Sharing a sentence is not in itself a finding about the gene and the disease.
cancer (continued). "Hypoxia inducible factor 1 subunit alpha (HIF-1-a) is the principal molecular mediator of the hypoxic response in cancer whereas EWSR1::FLI1 constitutes the oncogenic driver of EwS." (PMID 36915100, 2023). "This is consistent with emerging roles for this protein in the tumorigenesis of adult cancers and stimulation of expression by the EWSR1 proto-oncogene in several human cancers, including ES." (PMID 36765727, 2023). "One family with essential functions in RNA processing in cancer and NDs is the FET family of proteins, consisting of FUS, EWSR1, and TATA-Box Binding Protein Associated Factor 15 (TAF15)." (PMID 35731869, 2022). "In this study, we find that androgen signaling regulates the EWSR1 gene to produce different genetic outcomes important for cancer biology." (PMID 34409300, 2021). "With the advent of widely used modern molecular techniques during the last decades, it has become obvious that EWSR1 is involved in the development of diverse benign and malignant tumors with mesenchymal, neuroectodermal, and epithelial/myoepithelial features." (PMID 34203801, 2021). "With the advent of widely used modern molecular techniques during the last decades, it has become obvious that EWSR1 is involved in development of diverse benign and malignant tumors with mesenchymal, neuroectodermal, and epithelial/myoepithelial features." (PMID 34203801, 2021). "In the past decades, studies on EWSR1 have mainly focused on the role of fusion proteins formed by EWSR1 translocation in tumorigenesis and cancer development, whereas the biological function of EWSR1 itself remains poorly understood." (PMID 34612781, 2021). "Nevertheless, seldom studies have focused on the role of EWSR1 in cancers of epithelial origin, let alone in HCC." (PMID 34612781, 2021). "Of the many RBPs that bind to the KRAS 3′ UTR, AGO2, HuR (or ELAVL1), IGF2BP1/2/3, PUM2, EWSR1, TAF15, FUS, and TIA1 have been previously implicated in cancer." (PMID 26930719, 2016). "Deregulation of this gene has been described in several cancer cell lines, while a fusion transcript with EWSR1 has been detected in a panel of cancer cell lines of a small round cell sarcoma." (PMID 23329308, 2013). "This highly aggressive cancer is characterized by a chromosomal translocation that results in the formation of a gene fusion between the EWSR1 locus and an ETS transcription factor gene, which in 85% of the cases is FLI1." (PMID 19404404, 2009). "The inherent vulnerability of the EWSR1 gene to chromosomal breakage and translocation often results in its involvement in fusion events with different molecular partners, contributing to the development of diverse cancers." (PMID 40575153, 2025). "This retrospective case series describes two young adults (32–35 years old) without cancer predisposition or risk factors, diagnosed with EWSR1::PATZ1-fused NEpT." (PMID 40575153, 2025). "The prevalence of the EWSR1::CREM fusion gene in cancer has been estimated at 0.05%4." (PMID 36966162, 2023). "If the haploinsufficiency of EWSR1 contributes to the pathogenesis of these diseases, an approach involving modulation of the level of EWSR1 may be an effective approach to treating EWSR1-fusion expressing cancer patients." (PMID 36875767, 2023). "In addition, the related pathways of RUNX1 and EWSR1 include transcriptional misregulation in cancer." (PMID 35057728, 2022). "In both groups of these cancers, the CREB-family member is activated by being incorporated in the protein encoded by the fusion and by being placed under the control of the EWSR1 or FUS promoter, both of which are transcriptionally active in the cells of origin of these tumors." (PMID 36313756, 2022). "In summary, our findings identify LOXHD1, which is transcriptionally silent in the vast majority of normal and cancer cells, as a direct EWSR1::FLI1 target gene that plays an important role in cytoskeletal homeostasis, hypoxic adaptation, and oncogenic transcription in EwS." (PMID 35705030, 2022).
cancer (continued). "The EWSR1 gene rearrangement has been documented in both these types of cancers." (PMID 35346255, 2022). "circ-CUX1 knock-down inhibits aerobic glycolysis, proliferation, progression, and aggressiveness of NB. circ-CUX1 binds to EWSR1 to enable its contact with MAZ, leading to transactivation of MAZ and transcriptional modification of CUX1 and other genes linked with cancer progression." (PMID 33718173, 2021). "Despite the cancer relevance of EWSR1, its regulation is poorly understood." (PMID 34409300, 2021). "So far, no germline variants predisposing to cancer have been located in EWSR1." (PMID 33692755, 2021). "From this subset, we prioritized five candidates (PSMA3, EWSR1, LRRC1, HNRNPD, and FAM98A) based on their SNR rankings, established roles in cancer pathways (e.g., proteasome function, RNA processing, and transcriptional regulation)." (PMID 41472850, 2025). "We identified BLK as a kinase upregulated not only by EWSR1::WT1, but also in DSRCT cancer stem cell-like (CSC) culture conditions." (PMID 39139449, 2024). "The only known genetic alterations affecting TFCP2 in cancer are the recently discovered fusions to FUS and EWSR1 in atypical RMS." (PMID 38168093, 2024). "We analyzed the data on pulmonary malignant tumors between 2000 and 2019 in the Surveillance, Epidemiology, and End Results (SEER) database and reviewed all cases of pulmonary HCCC with EWSR1 fusion by searching PubMed." (PMID 37553667, 2023). "Using cancer cell line RNA-seq data, we first identified 516 genes that were commonly downregulated (>1 FPKM expression and ≥2-fold down) by EWSR1::FLI1 knockdown in three well-characterized EwS cell lines, SK-N-MC, A673, and CHLA-10." (PMID 35705030, 2022). "Interestingly21 showed that in GBM, EWSR1 was often fused with PATZ1, a cancer related gene, worsening the survival rates." (PMID 33762588, 2021). "For example, AGO protein is an RBP that serves as a platform of mRNA and small RNA interactions, and the FET family RBPs, including FUS, EWSR1 and TAF15, play important roles in RNA editing and human cancers." (PMID 24714572, 2014). "The FET family proteins (FUS, EWSR1 and TAF15) are abundant and highly conserved RBPs involved in cancer biology and other diseases." (PMID 24714572, 2014). "We discovered novel gene rearrangements in diverse human cancer types, including fusions of ROS1, SLC1A2, RAF1, EWSR1, CDK6, and CLTC." (PMID 23637631, 2013). "EWSR1 belongs to the FET (also known as TET) family of RNA-binding proteins, which is exposed to aberrations such as rearrangements and involved in the development of diverse benign and malignant tumors." (PMID 39148981, 2024). "Ideally, the effects of endogenous EWSR1::CREM protein would be studied in a cancer cell line that does not express CREM." (PMID 36966162, 2023). "The other benign or malignant tumor types harboring FUS or EWSR1 translocation show no gene amplification using FISH." (PMID 36555836, 2022). "We identified genes for which ASEs were observed in both the Afro-Caribbean cohort and the Jurkat cells expressing Tax or HBZ, including cancer genes EIF4A2, IKBKB, LZTR1, STAT6 (for Tax); CARS, MDM2, IKZF1 (for HBZ); and EWSR1, MUTYH, and PTPRC (for both Tax and HBZ)." (PMID 34543356, 2021). "Targeted deep-sequencing analysis of the tumors at sacrifice revealed that EF-targeted xenografted tumors analyzed 6 weeks after AdV injection were composed of non-edited (85%) or partially-edited (one locus; 12% of EWSR1 or 3% of FLI1) cancer cells." (PMID 33033246, 2020). "AKT2, BCL2, EWSR1 retrogene and MYCN for their cancer notoriety)." (PMID 30890123, 2019). "Hence, EWSR1 belongs to the FET (also known as TET) family of RNA-binding proteins, which is exposed to aberrations such as rearrangements and involved in the development of diverse benign and malignant tumors." (PMID 39148981, 2024).
cancer (continued). "However, without further testing, this result is not diagnostically conclusive because the EWSR1 gene is known to have multiple fusion partners depending on the cancer type." (PMID 35347250, 2022). "We identified new gene fusions involving ROS1, SLC1A2, RAF1, EWSR1, CDK6, and CLTC, some occurring in cancer types not previously known to harbor fusions." (PMID 23637631, 2013). "Additionally, the study included 11 cases of patients with the same EWSR1::CREB1 fusion, encompassing sarcomas not otherwise specified (NOS), malignant neoplasms of unknown primary, melanoma, and head and neck mucoepidermoid carcinoma." (PMID 38421462, 2024).
CNS tumors (11 papers, 2018 to 2025). "In conclusion, although the histopathological appearance of EWSR1::PATZ1 gene fusion CNS tumors is diverse, there are consistent imaging features." (PMID 39583630, 2024). "We compared the morphology, IHC results and molecular features with the previously reported EWSR1-PLAGL1 rearranged CNS tumors." (PMID 35912228, 2022). "In pediatric CNS tumors five different EWSR1 fusions have been detected, such as EWSR1–PLAGL1 and EWSR1–CREB1 (Online Resource 10)." (PMID 35169893, 2022). "As EWSR1::PATZ1 fusion CNS tumors might be a distinct entity, this study aims to investigate the imaging features in documented cases to identify common imaging patterns that may aid radiologists in suggesting a diagnosis." (PMID 39583630, 2024). "Imaging features of the EWSR1::PATZ1 gene fusion CNS tumors included in this study." (PMID 39583630, 2024). "Some of these EWSR1 rearrangements are fusions with the PLAGL1 gene, and other PLAGL1 gene rearrangements in CNS neoplasms have also been described." (PMID 38639853, 2024). "Two different PATZ1 partners, EWSR1 and MN1 have been identified in several different pediatric CNS neoplasms (Online Resource 15)." (PMID 35169893, 2022). "In conclusion, we describe five primary EWSR1-non-ETS fused CNS tumors exhibiting morphologic and biologic heterogeneity and we highlight the clinical importance of determining specific fusion partners to improve diagnostic accuracy, treatment and monitoring." (PMID 32997853, 2020). "Our study provides further insight into intracranial tumors with EWSR1-PLAGL1 fusion, representing a distinct CNS tumor with no-reported histological and immunohistochemical features." (PMID 35912228, 2022).
neurodegenerative disease (10 papers, 2016 to 2026). A disorder of the central nervous system characterized by gradual and progressive loss of neural tissue and neurologic function. "Missense mutations of EWSR1 in the central nervous system (CNS) are related to neurodegenerative diseases, such as amyotrophic lateral sclerosis." (PMID 37709831, 2023). "Mutations in various RNA binding proteins such as hnRNP A1, hnRNP A2/B1, FET protein family (FUS, TAF-15, EWSR1) Matrin-3, TIA-1 and Ataxin-244 are implicated in various neurodegenerative diseases." (PMID 29070802, 2017). "Consequently, our result improves the understanding of Ewsr1-regulated interactions or biological processes in the brain regions and neurodegenerative diseases at the proteome level." (PMID 37709831, 2023). "In addition, aggregation-enhancing mutations in EWSR1 and TAF15 are associated with ALS, suggesting that changes in the biology of these proteins are sufficient to drive neurodegenerative disease." (PMID 30068389, 2018). "We also present the complete list of human proteins with PrLDs and discuss the prevalence of the PrLD in nucleic-acid binding proteins that are often connected to neurodegenerative disease, including: ataxin 1, ataxin 2, FUS, TDP-43, TAF15, EWSR1, hnRNPA1, and hnRNPA2." (PMID 26996412, 2016).
infection (6 papers, 2008 to 2025). The state of being infected such as from the introduction of a foreign agent such as serum, vaccine, antigenic substance or organism. "Collectively, these data demonstrate that the TMER5-encoded mghv-miR-7 promotes the infection of germinal center B cells through targeted repression of the host transcript EWSR1." (PMID 31363027, 2019). "Consistent with this possibility, incorporation of anti-EWSR1 shRNAs into the miR-7-5p-deficient virus fully restored both naive B cell (9% WT versus 8% EW.shR) and germinal center B cell (79% WT versus 83% EW.shR) infection to levels equivalent to that of wild-type virus." (PMID 31363027, 2019). "Using novel, target-specific shRNA-expressing viruses, we determined that EWSR1 repression in vivo was essential for germinal center B cell infection." (PMID 31363027, 2019). "Using a novel technology, we demonstrated that repression of EWSR1 was essential for in vivo infection of the critical B cell reservoir." (PMID 31363027, 2019). "It is also plausible that EWSR1 functions to directly restrict germinal center B cell infection in some way." (PMID 31363027, 2019). "Finally, we analyzed the effect of infection on the cellular distribution of AldoA, EWSR1 and ILF3-90." (PMID 36306280, 2022). "Thus, 16 days after infection of wild-type B6 mice with control wild-type virus or viruses expressing scrambled or anti-EWSR1 shRNAs, splenocytes were harvested for B cell subset staining with CCF4-AM and with antibodies directed against the B cell surface markers CD19, GL7, and IgM." (PMID 31363027, 2019). "Both EWSR1 and ILF3-90 were strictly confined to the nuclei before infection, while in infected cells starting from the middle of the infectious cycle their localization was exclusively cytoplasmic." (PMID 36306280, 2022). "We identified here MHV68 mghv-miR-M1-7-5p as critical for in vivo infection and then validated host EWSR1 (Ewing sarcoma breakpoint region 1) as the predominant target for this miRNA." (PMID 31363027, 2019).
Benign Tumors (3 papers, 2015 to 2021). "Several malignant and benign tumors harbor an EWSR1 rearrangement due to the central role of EWSR1 in different cell processes and vulnerability of the gene as consequence of frequent transcription." (PMID 34203801, 2021). "The case provides an additional example of involvement of the EWSR1 gene in a benign tumor." (PMID 25875009, 2015).
EWSR1 also shares sentences with these, for which no sentence is quoted: alveolar rhabdomyosarcoma (17 papers); bone cancer (11); acute leukemia (6); lymphoma (5); alveolar soft part sarcoma (4); bone cyst (4); colon carcinoma (4); leiomyosarcoma (4); lung carcinoma (4); peripheral primitive neuroectodermal tumor (4); schwannoma (4); solitary fibrous tumor (4); adamantinoma (3); Childhood Cancer (3); fibrous histiocytomas (3); myelodysplastic syndrome (3); undifferentiated sarcoma (3); adenocarcinoma (2); adenoid cystic carcinoma (2); anaplastic astrocytoma (2); angiosarcoma (2); bone metastasis (2); Chondroid syringomas (2); chordoma (2); clear cell sarcoma of kidney (2); congenital fibrosarcoma (2); connective tissue tumors (2); epithelioid hemangioendothelioma (2); epithelioid sarcoma (2); femur (2).
A further 92 diseases each share a sentence with EWSR1 in 2 papers or fewer.